MGMT (O-6-methylguanine-DNA methyltransferase)
Diseases named in the same sentence as MGMT in open-access papers (continued):
Sharing a sentence is not in itself a finding about the gene and the disease.
tumor (continued). "As a consequence, tumours with epigenetic silencing of MGMT gene become more sensitive to the killing effects of alkylating agents." (PMID 21269507, 2011). "Based on comparisons using standard methylation-specific PCR and immunohistochemical studies using the anti-MGMT antibody, we determined 14% as the threshold distinguishing unmethylation from methylation of the MGMT promoter in a given tumor." (PMID 21829728, 2011). "LINE-1 methylation and MGMT promoter methylation were also correlated with tumor grading; LGGs displayed a higher methylation level of LINE-1 and the MGMT promoter than GBMs (WHO grade 4)." (PMID 21829728, 2011). "In both studies, MGMT activity was successfully inhibited in peripheral blood mononuclear cells and even in tumour tissues in the CWRU Study." (PMID 21811257, 2011). "Over time, variations in the methylation status of MGMT promoter within the same tumour have also been described, although the relevance of these events is unclear." (PMID 21269507, 2011). "Because little is yet known about possible differences between MGMT promoter methylation of different metastases or over the clinical course, we analysed the MGMT methylation status of primary tumours and subsequent metastases of a patient." (PMID 20736948, 2010). "Baseline tumour MGMT activity varied significantly between patients, as well as between sections of a tumour biopsy in the same patient." (PMID 20628383, 2010). "The MGMT protein expression more than MGMT promoter methylation status predicts the response to TMZ in human tumour cell lines." (PMID 20517307, 2010). "As with the first experiment, by day 6 MGMT activity in tumour was effectively suppressed in both groups, and rapidly returned to pretreatment levels after the completion of treatment in the schedule A group." (PMID 20628383, 2010). "In contrast, tumour extracted from animals treated with the dose-intense schedule was noted to have near complete suppression of MGMT activity throughout treatment." (PMID 20628383, 2010). "The influence of temozolomide treatment on MGMT activity in tumour was then evaluated in mice with established flank GBM43 tumours." (PMID 20628383, 2010). "Kaplan–Meier curves revealed median OS of 10.5 months (95% CI: 7.2–12.5) for patients whose tumours were methylated at the MGMT promoter compared with a median of 9.7 months (95% CI: 7.6–11.4) for patients with an unmethylated MGMT promoter." (PMID 20736948, 2010). "Common between the two studies was discordance in several patients between changes in MGMT activity in PBMCs and tumour." (PMID 20628383, 2010). "In the days after completion of 5 days of treatment on the standard dose arm, MGMT activity in tumour rapidly returned to pretreatment levels." (PMID 20628383, 2010). "They found a survival benefit for patients whose tumours were both MGMT promoter hypermethylated and PTEN positive indicating that lack of survival signalling benefits therapy response in the absence of DNA repair." (PMID 20515495, 2010). "Combined bisulphite restriction analysis evaluation of these samples revealed different grades of MGMT promoter methylation of the tumour DNA: 76 of 122 biopsy samples (62.3%) were unmethylated and 46 (37.7%) were methylated." (PMID 20736948, 2010). "In conclusion, MGMT protein expression more than the level of MGMT promoter methylation predicts the response to TMZ in human tumour cell lines." (PMID 20517307, 2010). "Nu/nu mice were inoculated with GBM43 tumour and treated exactly as described in the first experiment, with the exception of the choice of time points for evaluation of tumour MGMT activity." (PMID 20628383, 2010). "After treatment with temozolomide, mean MGMT activity in tumour was depleted to 56% of pretreatment levels." (PMID 20628383, 2010). "Transcriptional silencing of the MGMT gene by promoter methylation has been shown in cell lines as well as in human tumour tissues." (PMID 20517307, 2010).
tumor (continued). "The remaining patients typically have normal, or even increased tumour MGMT expression, and 2-year survival in this group is dismal, at <15%." (PMID 20628383, 2010). "A recognized predictor for tumour response to temozolomide is the epigenetic silencing of the O6-methylguanine-DNA-methyltransferase (MGMT) gene promoter by methylation." (PMID 20515495, 2010). "Dose-intense temozolomide prolongs tumour MGMT activity depletion compared with standard dosing, however, survival was not improved in this model." (PMID 20628383, 2010). "Increased H3K9 tri-methylation levels are associated with the silencing of tumor suppressor genes such as P16, P14, MLH1 and MGMT in cancer cells." (PMID 21192791, 2010). "In that seminal study, hypermethylation of the MGMT gene was observed in 46% of tumors as well as in 50% of normal appearing colorectal mucosa samples of patients in whom MGMT promoter methylation was found in the corresponding tumor." (PMID 20098741, 2010). "Mice were treated with temozolomide at 50 mg kg−1 daily for 5 days, and at serial time points (days 0, 1, and 7 after treatment), animals were killed and MGMT activity was assessed in flank tumour." (PMID 20628383, 2010). "This DNA damage can be repaired by O-6-methylguanine-DNA methyltransferase (MGMT) expressed in some tumor cells, which is the primary mechanism of tumor resistance to alkylating agents, including temozolomide." (PMID 21173727, 2010). "Overall, our understanding of the kinetics of MGMT activity depletion by alkylating agents in normal tissues and tumour are limited." (PMID 20628383, 2010). "Tumor hypermethylation of the MGMT gene enhancer region and the RASSF1A gene promoter region were identified as variables independently associated with a five-fold increased risk of developing multiple lesions." (PMID 20098741, 2010). "After treatment with temozolomide on either standard dose (schedule A, 200 mg m−2 for 5 days) or dose-intense (schedule B, 100 mg m−2 for 21 days) schedules, MGMT activity in tumour was maximally depleted within 3–6 days after initiation of therapy." (PMID 20628383, 2010). "Two previously reported studies have attempted to examine the effect of dose-intense temozolomide regimens on MGMT activity in tumour." (PMID 20628383, 2010). "Three days after the initiation of treatment, both schedules depleted tumour MGMT activity to <5% of pretreatment levels." (PMID 20628383, 2010). "Tumour cells frequently express high levels of MGMT, and pre-clinical studies identify the protein as a key determinant of cell survival." (PMID 19367282, 2009). "Consistent with previous observations, we obtain a large cluster of samples in which the MGMT promoter is unmethylated and a smaller cluster consisting of tumor samples with methylated MGMT promoters." (PMID 19804638, 2009). "MGMT immunoreactivity and promoter methylation status in the individual tumor subgroups of brain metastases." (PMID 19274096, 2009). "The high DNA repair activity of tumor cells expressing active MGMT is believed to defend the tumor from the cytotoxic effects of alkylating agents." (PMID 19274096, 2009). "We examined the methylation status of p16INK4A, RASSF 1A and methylguanine methyltransferase (MGMT) genes considered to be inactivated by promoter methylation in several tumours." (PMID 22276000, 2009). "Early recovery of MGMT activity in tumours suggested that more protracted dosing with LM is required." (PMID 19367283, 2009). "The rationale for the current study came from the phase 2 trial involving lomeguatrib and temozolomide, where we observed recovery of tumour MGMT activity within 24 h of completing treatment." (PMID 19367282, 2009). "MGMT levels in tumours have been measured by the assessment of protein and gene expression, analysis of enzyme activity or investigation of epigenetic silencing through promoter methylation." (PMID 19536096, 2009).
tumor (continued). "A significant correlation of homogeneous MGMT-immunoreactivity (>95% MGMT positive tumor cells) and an unmethylated MGMT promoter was found." (PMID 19274096, 2009). "TMZ showed the best efficacy in patients with a methylated O6-methylguanine-DNA methyltransferase (MGMT) promoter by eliminating more sensitive differentiated tumor cells and in part stem cell-like tumor cells." (PMID 19725960, 2009). "Patients were classified into 3 groups according to the dose of fotemustine received, from the lowest dosage received in group A, to the highest in group C. Analysis of MGMT promoter methylation in tumor tissue was successfully performed in 19 patients." (PMID 19335893, 2009). "The dose of LM given to subsequent patients was increased from 40 to 60 mg and then 80 mg to try to achieve complete tumour MGMT inactivation." (PMID 19367283, 2009). "Tumours biopsied on the last day of treatment showed complete inactivation of MGMT but there was recovery of activity in tumours sampled later." (PMID 19367283, 2009). "Many tumours express high levels of MGMT and dose-limiting toxicities occur in the bone marrow, which expresses low levels of MGMT." (PMID 19367283, 2009). "A separate analysis of the individual tumor subgroups generally confirmed that MGMT immunopositivity correlates with an unmethylated MGMT promoter." (PMID 19274096, 2009). "Further, quantitative MGMT methylation was assessed and these results were then correlated with survival and tumor recurrence." (PMID 19807915, 2009). "Here we present the detailed pharmacodynamic (PD) analysis from that study, which used a 5-day LM/TMZ treatment schedule, and show that there was post-LM/TMZ recovery of tumour MGMT activity." (PMID 19367283, 2009). "In 8 of 13 tumor samples all three techniques produced homogeneous results (4 unmethylated and 4 methylated MGMT promoters)." (PMID 18298842, 2008). "Tumour cell resistance to O6-alkylating agents is conferred by the DNA repair protein O6-methlylguanine-DNA alkyltransferase (MGMT)." (PMID 18475294, 2008). "At 2 years, 46% of patients who received the combined study treatment and whose tumours had a methylated MGMT promoter gene survived compared with only 14% of patients with an unmethylated MGMT gene (p=0.0001)." (PMID 22275966, 2008). "MGMT has a special place in this context, as, although it has a poor specific prognostic value, it can be used to predict the chemosensitivity of these tumours." (PMID 18506188, 2008). "High levels of MGMT activity in tumor cells create resistance by blunting the therapeutic effect of TMZ, leading to treatment failure." (PMID 17683572, 2007). "The immunohistochemical study of the initial tumor specimen confirmed positive MGMT protein expression." (PMID 17683572, 2007). "With the exception of MGMT where the methylation prevalence was lower in the tumours than sputum, the positive predictive value for the other four genes was 45–72%." (PMID 17406356, 2007). "Resistance to TMZ is considered to be mediated, at least to some extent, by a DNA repair enzyme, MGMT (O6-methylguanine-DNA methyltransferase), which is induced in the tumor." (PMID 17683572, 2007). "The MGMT protein expression of the tumor specimen taken at the initial surgery was performed using immunohistochemical method." (PMID 17683572, 2007). "The percentages of patients under 50 years, with an MMSE above 27 or with a unifocal tumour location are higher in patients with a MGMT status." (PMID 17609661, 2007). "Some previous reports demonstrated the epigenetic regulation of MGMT expression by treating tumor cell lines with 5-aza-dC and testing the MGMT levels by RT-PCR." (PMID 17547775, 2007). "MGMT level varies considerably in normal and tumor cells, and cells that exhibit a low MGMT level are more sensitive to CENU." (PMID 16287507, 2005).
tumor (continued). "We have examined the effect of the modified guanine base, O6-(4-bromothenyl)guanine (PaTrin-2, PatrinTM, Lomeguatrib) on MGMT activity and cell or xenograft tumour growth inhibition by temozolomide in the human breast carcinosarcoma cell line, MCF-7." (PMID 16278661, 2005). "In both cases, the qPCR data suggested a low-level over-representation of the AURKB genomic locus in the tumour DNA relative to control levels :patient 224 : 1.9 and 1.7-fold and patient 230 : 2.9 and 2.5-fold (against MGMT and HGG1, respectively)." (PMID 16222316, 2005). "In 20 of the patients more than one metastasis was analysed, and in nine of these cases the MGMT expression differed between tumours in the same individual according to the 50% cutoff level." (PMID 14562026, 2003). "Among 53 patients treated with DTIC alone, there was a similar tendency of improved clinical response in patients whose tumours had low MGMT expression." (PMID 14562026, 2003). "Clinical studies of the relationship between MGMT levels and response to chemotherapy have given differing results in different tumour types." (PMID 14562026, 2003). "MGMT-negative tumours showed very frequent and widespread methylation in the promoter compared with MGMT-positive tumours." (PMID 12592365, 2003). "In patients with exon 3 SNPs, a larger proportion of tumours with high MGMT expression was 89% (eight out of nine) compared to 67% (29 out of 43) without these SNPs (P=0.19, Fisher's test)." (PMID 14562026, 2003). "Among all 79 patients, 65 of whom were included in our earlier study, there were nine responders (41%) in 22 patients with tumours with low MGMT expression, while there were 11 responders (19%) in 57 patients carrying tumours with high expression of MGMT." (PMID 14562026, 2003). "Owing to tumour heterogeneity, a possible future strategy to obtain a more correct evaluation of MGMT levels in relation to clinical response to DTIC-based treatment is to analyse multiple tumours in patients using fine-needle biopsies." (PMID 14562026, 2003). "As for MGMT expression, MGMT-negative tumours showed high frequency and widespread methylation compared with MGMT-positive tumours and normal liver." (PMID 12592365, 2003). "Inactivations of DNA repair genes, O6-methylguanine-DNA methyltransferase (MGMT) and hMLH1, by promoter hypermethylation have been reported in several types of primary human neoplasia." (PMID 12592365, 2003). "Among the cases with a loss of MGMT expression, 76.5% were methylated while 6.1% of tumours were methylated in cases showing MGMT expression." (PMID 12085181, 2002). "Also, MGMT promoter methylated and unmethylated tumors exhibited similar mean tumor volumes (96 vs. 103 cm3)." (PMID 41597253, 2026). "Although the specific covariates varied among studies, commonly adjusted variables comprised age, sex, baseline performance status (e.g., WHO or KPS), extent of resection, tumor grade, molecular markers (e.g., IDH mutation and MGMT promoter methylation status), and treatment modality." (PMID 41491296, 2026). "We hypothesize that sustained pretreatment with inhaled CBD will attenuate tumor growth by inducing apoptosis, suppressing cell proliferation, and downregulating chemoresistance mechanisms such as MGMT expression." (PMID 41596406, 2026). "Key outcomes include reduced tumor burden and modulation of molecular markers associated with tumor stemness (SOX2), immune evasion (PD-L1, IDO), cellular proliferation (Ki67), and chemoresistance (MGMT)." (PMID 41596406, 2026). "As shown in the CCTG CE.6/EORTC 26,062 − 22,061 trial, elderly HGG patients may benefit from the addition of temozolomide to short-term RT, particularly when the tumor exhibits MGMT promoter methylation." (PMID 41039275, 2025). "Additionally, gene expression levels from the OncoDB database were presented, showing consistency with data from UALCAN, except for MGMT, which exhibited downregulation in tumor tissues." (PMID 40282990, 2025).
tumor (continued). "Thus, our results provide an additional argument for using MGMT expression as a biomarker for predicting tumor sensitivity to treatment." (PMID 40509165, 2025). "Modern neuro-oncology classifies tumors, like diffuse gliomas, by markers such as IDH mutation, 1p/19q co-deletion, methylguanine-DNA methyltransferase (MGMT) status, and others; features that not only predict prognosis but also influence how a tumor interacts with the brain." (PMID 40647472, 2025). "Decitabine has been shown to restore MGMT expression in previously methylated tumor cells." (PMID 40895460, 2025). "Patient #1 had a methylated MGMT and experienced halted tumor growth." (PMID 40295665, 2025). "However, when the ERK pathway was blocked by vMF at the same time, the compensation of MGMT protein was insufficient, which was disadvantageous to the DNA repair of tumour cells." (PMID 39873425, 2025). "Distinct tumor regions may exhibit variable MGMT levels, leading to localized differences in immune cell activity, chemoresistance, and immunotherapeutic response." (PMID 40895460, 2025). "MGMT methylation may also influence the cellular makeup of the tumour, affecting the distribution of necrotic areas and enhancing/non-enhancing regions." (PMID 40282434, 2025). "Among the 26 patients in the MGMT unmethylated group, 2 (7.7%) experienced tumor recurrence." (PMID 40963873, 2025). "Research on TMZ treatment resistance has identified several contributing factors, such as elevated levels of MGMT (O6-methylguanine-DNA methyltransferase), increased activity of DNA repair pathways, the presence of tumor stem cells, and the role of drug efflux transporters." (PMID 40813374, 2025). "Quite interestingly, MGMT promoter methylation status may also impact the tumor's ability to maneuver lipid metabolism." (PMID 39992790, 2025). "Future strategies may include tumor-specific delivery systems, prodrugs, or nanotechnology-based carriers to selectively suppress MGMT in cancer cells while minimizing adverse effects on healthy tissues." (PMID 40895460, 2025). "Therefore, MGMT protein has emerged as a central determinant of tumor resistance to several clinically used anticancer alkylating agents and is an ideal target for biochemical modulation." (PMID 39997039, 2025). "Exploring how MGMT expression alters tumor-immune interactions could reveal opportunities to combine DNA repair inhibitors with immunotherapies to enhance anti-tumor efficacy." (PMID 40895460, 2025). "Integrating these features with patient-specific molecular and genetic profiles (e.g., IDH mutation status, MGMT promoter methylation, EGFR amplification, TERT promoter mutations) allows for non-invasive prediction of tumor biology, prognosis, and potential treatment response." (PMID 41465586, 2025). "Such metabolic changes may lead to homogenization of the tumor microenvironment, which in turn masks the effect of MGMT promoter methylation on cell density." (PMID 40958862, 2025). "At least four of the five patients had MGMT promoter methylated GBM tumours as well." (PMID 40668315, 2025). "MGMT promoter hypermethylation increases tumor responsiveness to treatment with temozolomide." (PMID 39839210, 2025). "Loss of MGMT protein from tumor cells also occurred after spermine NONOate treatment, but not with spermine showing the specificity." (PMID 39997039, 2025). "Notably, 42% of the 142 methylation‐regulated tumour genes are controlled by multiple methylation sites, especially MGMT (14 sites), AATK (12 sites), VRK2, and FGFR2 (10 sites)." (PMID 41292185, 2025). "Together with our data, this raises the question of whether MGMT methylation may be a secondary event during early carcinogenesis, directing a different tumor biology." (PMID 39980037, 2025). "We also found the total-tumor/edema ratio to be higher in non-MGMT promoter methylated tumors." (PMID 41476598, 2025).